FOXA1 (forkhead box A1)
Diseases named in the same sentence as FOXA1 in open-access papers (continued):
Sharing a sentence is not in itself a finding about the gene and the disease.
breast carcinoma (continued). "FOXA1 mutations in breast cancer samples were 20.69% A > G, 19.54% C > T, 19.54% G > A, and 16.09% G > C." (PMID 31562808, 2019). "In the present study, FOXA1 and Nestin expression in breast cancer metastases was associated with specific breast cancer subtypes (luminal phenotype versus triple-negative breast cancer metastases)." (PMID 30819139, 2019). "In contrast, the closest baseline method (Trace Lasso) only selected 1 gene (FOXA1) with a somatic mutation known to be associated with breast cancer." (PMID 30184048, 2019). "We show that aberrant DNA hypomethylation of promoter regions is one of the mechanisms underlying the aberrant expression of FOXA1 in ER+ breast cancer." (PMID 31562808, 2019). "FOXA1 in our cohort was negatively associated with the Ki-67 proliferation index, in agreement with data reported in human breast cancer." (PMID 31888566, 2019). "This suggests that genes associated with FOXA1/DIV locations are sensitive to perturbation of pathways relevant to cancer progression in particular in breast cancer models." (PMID 29669022, 2018). "Briefly, this dataset contains 44SNPs associated with breast cancer, among which 29 are related to the modulation of FOXA1,a DNA-binding proteins crucial for nucleosome positioning and chromatin accessibility." (PMID 29069282, 2018). "FOXA1 is a transcription factor that is associated with ER+ breast cancer and luminal breast carcinoma." (PMID 29983747, 2018). "We find that cPRC1 complexes functionally associate with ERα and its pioneer factor FOXA1 in ER+ breast cancer cells, and with BRD4 in triple-negative breast cancer cells (TNBC)." (PMID 30139998, 2018). "With this, we show divergent clinical correlations of the two ERα pioneer factors FOXA1 and GATA3 in metastatic breast cancer, where endocrine therapy resistance was associated with decreased FOXA1 levels in pleural metastases." (PMID 29972720, 2018). "We previously used a VSE-based approach to identify the enrichment of Breast Cancer (BCa) genetic predispositions at enhancers bound by FOXA1 and ESR1 in breast cancer cells." (PMID 28239419, 2017). "Among all the SNPs associated with breast cancer, the rs4784227 is one of the risk-associated SNPs that is believed to disrupt the binding of FOXA1 to accessible chromatin." (PMID 28361702, 2017). "Previous studies have demonstrated that breast cancer associated SNPs are quite enriched for the binding sites of a transcription factor called FOXA1, which is crucial for chromatin accessibility and nucleosome positioning." (PMID 28361702, 2017). "The purpose of the present study was to explore the genetic expression patterns and associations between AR and FOXA1 by ER status determined from web-based breast cancer datasets." (PMID 29137314, 2017). "In conclusion, the present results indicate that AR and FOXA1 are closely associated in breast cancers, and distinctive clinicopathological features are presented in ER-positive tumors according to AR and FOXA1 status." (PMID 29137314, 2017). "Elevated FOXA1 expression is associated with a better prognosis and sensitivity to hormonal therapy in breast cancer patients." (PMID 26797644, 2016). "RNA and protein analysis of a panel of breast cancer cell lines revealed that BRCA1 deficiency is associated with the downregulation of FOXA1 expression." (PMID 25531315, 2015). "FOXA1 is highly expressed in luminal subtype breast cancer, and its deficiency promotes the metastasis of this subtype cancer." (PMID 25848863, 2015). "Importance of FOXA1 gene was defined before in cell transcription in different mutations in acute myeloid leukemia and also offered as a promising prognostic marker in breast cancer." (PMID 25913414, 2015). "These three TFs bind to each other's promoter regions, and importantly the FOXA1-mediated DNA-binding capacity of ERα relates to breast cancer risk." (PMID 24792166, 2014).
breast carcinoma (continued). "The closest correlation is the mutations in the FOX family, in which FOXA1 is somatically mutated in sporadic breast cancer and FOXP1 is germline-mutated in the BRCA1+ family." (PMID 24884718, 2014). "Given the association of early neoplasias with ER + breast cancers, we wished to further characterize two important transcription factors, FOXA1 and GATA3, thought to act upstream of ER in the estrogen response pathway." (PMID 24887547, 2014). "For example, breast-cancer-associated SNPs map to enhancers bound by the forkhead box A1 (FOXA1) TF and ERα, and modulate the affinity of FOXA1 for DNA, resulting in altered target gene expression." (PMID 25473436, 2014). "FoxA1 expression is associated with ERα positivity in breast cancer and FoxA1 is one of the minimal set of genes that define ERα-positive luminal cancer." (PMID 24049078, 2013). "FOXA1 is a necessary pioneer factor to mediate ER alpha association with compacted DNA in breast cancer cells." (PMID 23885756, 2013). "These evidences imply that high FOXA1 expression is linked with survival and a better outcome in breast cancer patients." (PMID 23192763, 2013). "By contrast, in breast cancer, there is a clear association between high FOXA1 expression and a better survival." (PMID 23192763, 2013). "In contrast, the FoxA1-dependent estrogen target genes are significantly associated with only one poor-outcome expression signature (mortality) from breast cancer." (PMID 22125492, 2011). "Included among these are Sirt1, Hey2, Ncoa4, and Foxa1, all of which have been implicated in the progression of luminal breast cancer and ER-α-dependent signaling, as well as ER-α (that is, Esr 1)." (PMID 20565980, 2010). "Patients with loss of FOXA1 tumour expression showed an increased risk for breast cancer recurrence compared with the patients that were positive for this marker." (PMID 19549328, 2009). "In the subset of ERα-negative patients, those who were FOXA1-negative had a 3.61-fold increased risk of breast cancer recurrence when compared with the FOXA1-positive." (PMID 19549328, 2009). "Notably, FOXA1 and RAB25 are strongly implicated in breast cancer biology, and FOXA1 has been directly linked to the aryl hydrocarbon receptor (AHR), the main regulator of CYP1A1." (PMID 41901204, 2026). "Allele-specific variant scoring identified breast cancer risk variants with strong allele-dependent effects, and attribution-based motif discovery revealed enrichment of FOXA1-associated motif features, consistent with FOXA1 upregulation in primary tumors." (PMID 42182259, 2026). "FOXA1 mutations in the wing domains have been previously identified and shown to produce distinct chromatin profiles that influence therapeutic response in breast cancer." (PMID 41224124, 2025). "Notably, the F254 residue, which plays a crucial role in stabilizing the α-helix at the C-terminus of the FKHD domain of FOXA1, is deleted in a substantial fraction of prostate and breast cancer-associated indels." (PMID 39633177, 2025). "Moreover, such duality has also been observed in the same FOX gene, where overexpression of FOXA1 is associated with a favorable prognosis for breast cancer while indicates a poor clinical outcome for prostate cancer." (PMID 37401400, 2023). "Moreover, we aimed to examine the association of the combination of AGR2 and FOXA1 with the prognosis of breast cancer." (PMID 37568077, 2023). "Furthermore, FOXA1 form a transcriptional network with ERα and some other factors to control the susceptibility genes in breast cancer." (PMID 36009407, 2022). "In our recent work, we comprehensively evaluated the association of genetic variations of TF occupancies with breast cancer risk using generalized mixed models and found that risk-associated (susceptible) TFs, such as master regulator FOXA1, significantly contributed to breast cancer susceptibility." (PMID 36402776, 2022).
breast carcinoma (continued). "Studies of hormone-regulated cancers, such as breast cancer and prostate cancer, have shown that pathogenic dysregulations of gene expression are mediated through risk variants altering binding affinities of master TFs, such as FOXA1, ESR1, and AR." (PMID 36402776, 2022). "Notably, increased expression of FOXA1 is also associated with therapy resistance in this breast cancer subtype." (PMID 34680352, 2021). "While thwarting FOXA1 expression may provide utility in breast cancer, it is also important to note that loss of FOXA1 can induce more primitive cell behaviors." (PMID 34680352, 2021). "Moreover, enhancer regions selectively activated in metastatic breast cancer are associated with FOXA1 transcriptional programs." (PMID 34680352, 2021). "Notably, FOXA1 is expressed specifically in breast cancer cells and is associated with open chromatin and ERα expression." (PMID 34202157, 2021). "Notably, FOXA1 also facilitates AR-chromatin association in prostate development and cancer as well as in breast cancer cells." (PMID 34680352, 2021). "In this context, FOXA1 is a pioneering factor for multiple nuclear hormone receptors and is associated with favorable patient outcomes, particularly in ER expressing luminal breast cancers, which represent the majority of cases." (PMID 34680352, 2021). "Deep sequencing of 300 primary breast cancers revealed recurrent hotspot mutations in the FOXA1 promoter that coincide with increased expression, suggesting that these mutations drive elevated transcription of FOXA1." (PMID 34680352, 2021). "FOXA1 overexpression in luminal breast cancer cell lines fundamentally alters the enhancer landscape, activating transcriptional programs associated with oncogenic signaling pathways similar to those observed in clinical breast cancer specimens." (PMID 34680352, 2021). "This association, and the recent description of FOXA1 as a determinant of chemotherapy resistance in breast cancer cells, strengthen the rationale of trials to evaluate the combination of androgen receptor-targeting agents with new-generation anti-HER2 targeted therapies." (PMID 34885167, 2021). "The identical FOXA1 promoter mutation is reported to be a hotspot mutation in breast cancer, albeit mutated in <1% of patients, and is known to upregulate the transcription of this gene and to give a growth advantage to breast cancer cells under anti-estrogen receptor therapy in vitro." (PMID 32235312, 2020). "Cross talk between FOXA1 and ER can favor the expression of differentiation-associated genes, and not the proliferation-associated genes that results in well differentiated breast carcinomas with estrogen receptor positivity, which per se indicates a good prognosis." (PMID 30819139, 2019). "Thus, the potential functional variant identified in this study on the promoter region of FOXA1 (rs35237183) represents a good candidate variant for breast cancer susceptibility; however further studies are needed to confirm this." (PMID 30823486, 2019). "Our findings suggest that the aberrant DNA hypomethylation of promoter regions is one mechanism underlying the aberrant expression of FOXA1 in ER+ breast cancer, which might be a potential indicator of favorable prognosis." (PMID 31562808, 2019). "Furthermore, we identified the mutation and methylation status of FOXA1 in breast cancer to improve the characterization of malignant cells and thereby predict treatment response and prognosis." (PMID 31562808, 2019). "FOXA1 is mutated in 1.8% of breast cancers and 3–5% of prostate cancers." (PMID 30819139, 2019). "Mutations in the promoter of FOXA1 that cause its overexpression through increased E2F binding constitute a second documented example of a biologically relevant mutation in a cis‐element in some breast cancer genomes." (PMID 31304632, 2019).
breast carcinoma (continued). "Thus, in this article, we tried to investigate the association between 16q region including TOX3/LOC643714 locus, which interacts with FOXA1, and breast cancer risk in a cohort of Iranian population." (PMID 31338012, 2019). "This suggests a loss of the normal interplay between FOXA1 and ER in feline mammary carcinomas." (PMID 31888566, 2019). "TOX3 and FOXA1 proteins are believed to be involved in the susceptibility of breast cancer." (PMID 31338012, 2019). "Similarly, mutations in the promoter of FOXA1, a known gene driver in breast cancer, were found to increase E2F binding using TFM-pvalue." (PMID 29456552, 2018). "Interestingly, although overexpression of FOXA1 is associated with poor prognosis in prostate cancer, ERα-positive breast cancer with high FOXA1 expression shows favorable sensitivity to endocrine therapy." (PMID 28264478, 2017). "Moreover, the DNA sequence of this region is evolutionary conserved, contains FOXA binding motifs, and coincides with ENCODE FOXA1 ChIP-seq peaks in HepG2 hepatocellular carcinoma and T-47D breast cancer cells." (PMID 29155818, 2017). "Inactivating mutations of FOXA1 have been observed in breast cancer by exome sequencing study." (PMID 27835577, 2016). "In breast cancer if these mutations do diminish the binding capability of FOXA1, ER's dependency upon FOXA1 for binding suggests that these tumors may have evolved to become independent of oestrogen for growth." (PMID 23420418, 2013). "The association of ER alpha and FOXA1 with breast cancer have been well defined." (PMID 23885756, 2013). "In addition, it also detected the activity difference of two other breast cancer associated TFs, FOXA1 and GATA3, in ER+ versus ER- samples." (PMID 23885756, 2013). "The same study described a FOXA1 binding site at breast cancer SNP rs4784227, whose risk allele segregates with the risk allele of rs3803662; FOXA1 preferentially bound the site that included the rs4784227 risk allele resulting in a 5-fold decrease in TOX3 expression." (PMID 23270421, 2012). "These authors claim that FOXA1 can serve as a clinical marker for the luminal A subtype, and that its prognostic ability in these low-risk breast cancers may prove to be useful in clinical treatment decisions." (PMID 19549328, 2009). "FOXA1 expression, however, is able to stratify this relative risk among this subset of carcinomas, since its loss accounts for a 3.61-fold increased risk for breast cancer recurrence." (PMID 19549328, 2009). "Deletion of the FOXA1 gene resulted in a dramatic loss of tumor cell migration ability in the hormone-receptor-positive breast cancer (HR+ BC) cell lines MCF-7 and T47D." (PMID 39000600, 2024). "As a result of the dynamic cooperation between FOXA1 and nuclear receptor function, loss of FOXA1 expression is sufficient to restrict ER and AR transcriptional activity, cell proliferation, and tumor growth in ER+ breast cancers and AR+ prostate cancers, respectively." (PMID 37691854, 2023). "Of note, class I FOXA1 mutations are also more frequently associated with invasive lobular breast cancer than ductal disease and may suggest a different role for these mutations in different breast cancer subtypes." (PMID 34680352, 2021). "Combining data from TCGA, analyses of the DAR sequences associated with the DNA-binding motifs of significantly enriched TF families including AP-1, TEAD and FOX, indicated that the loss-function of FOXA1 might play a critical role in doxorubicin-resistant breast cancer cells (DOX-R BCCs)." (PMID 34395436, 2021). "In addition, breast cancer risk–associated SNPs are enriched in the cistromes of FOXA1 and ESR131." (PMID 32127627, 2020).
breast carcinoma (continued). "Considering that PGR (the PR-encoding gene) is a direct ER target gene, and FOXA1 is a critical pioneer factor for ER, it can be hypothesized that Sox2 altered ER transcriptional activity in FMCs of the present study as it does in breast cancers." (PMID 33553286, 2020). "In addition, the expression levels of FOXO3 and FOXA1 may also be useful biomarkers to molecularly classify BRCA1-mutated breast cancers." (PMID 27043660, 2016). "Furthermore, the association between FOXA1 and ER in breast cancer and FOXA1 and androgen receptor (AR) in prostate cancer suggests that expression levels of FOXA1 may influence responsiveness to antihormonal treatment in hormone dependent cancers." (PMID 24849812, 2014). "Integration of the FOXA1 knockdown-induced and drug-induced gene expression profiles identified 63 candidate compounds for treatment of breast cancer, including 18 approved drugs, with recovery of the known breast cancer therapy fulvestrant." (PMID 42182259, 2026). "We also evaluated FOXA1 expression across various tumour types and observed positivity in 25 of 44 (57%) breast carcinomas, 15 of 68 (22%) urothelial carcinomas and rarely in other tumour types." (PMID 42098986, 2026). "FOXA1 overexpression has been implicated in genome‐wide enhancer reprogramming and expansion in tumours, such as in ER+ breast cancer, where FOXA1‐mediated activation of a HIF‐α super‐enhancer activates a pro‐metastatic transcription program." (PMID 39887412, 2026). "To validate that the effect of FOXA1 deacetylation upon HER2/HER3 activation is less likely dependent on ER, we evaluated the expression of genes associated with worse prognosis in breast cancer upon heregulin and fulvestrant treatment for 3 h." (PMID 41224124, 2025). "Research indicated that the transcriptional regulatory network involving estrogen receptors alpha (ESR1), GATA3, and FOXA1 plays a significant role in the development of breast cancer." (PMID 40003882, 2025). "For instance, the stable expression of FOXA1 in mesenchymal breast cancer cells was found to induce the epithelial marker E-cadherin at both mRNA and protein levels." (PMID 40216647, 2025). "Prior research in multiple ER-positive breast cancer cell lines has shown that FOXA1, functioning as a pioneering transcription factor, aids in opening chromatin and then attracting AR or ER to nearby promoter regions of UGT2B15 genes." (PMID 39856707, 2025). "MGAT4EP, a newly identified pseudogene, is localized in the cell nucleus and interacts with FOXA1, a key regulatory factor in breast cancer." (PMID 40069131, 2025). "The downregulated genes (ESR1, AR, SPDEF, and FOXA1) participate in hormone receptor signaling and epithelial integrity in breast cancer." (PMID 41462902, 2025). "FOXA1 can facilitate the binding of ER and AR to their target genes, which is particularly important in luminal breast cancer." (PMID 40003882, 2025). "Three genes (FOXC1, EN1, and ELF5) stood out by displaying a pattern opposite to that of FOXA1, with hypomethylation and expression in Basal tumors, but hypermethylation and repressed expression in all other breast cancer subtypes." (PMID 40155623, 2025). "These all indicate that the suppression of FOXA1 expression by Twist1 plays a substantial role in the Twist1-driven migration, invasion, and metastasis of breast cancer cells." (PMID 40003882, 2025). "FOXA1 acts as a pioneer factor, facilitating the expression of most ER-regulated genes during the initiation and progression of luminal breast cancers." (PMID 41224124, 2025). "We were specifically interested in discovering NR transcription factors in PDAC, similar to what is observed between FOXA1 and ESR1 in breast cancer and between FOXA1 and AR in prostate cancer." (PMID 41168397, 2025). "Research has shown that FOXA1 can affect the subtype and prognosis of breast cancer by binding and expressing ER." (PMID 40003882, 2025).